TRAF2 (TNF receptor associated factor 2)
Diseases named in the same sentence as TRAF2 in open-access papers (continued):
Sharing a sentence is not in itself a finding about the gene and the disease.
tumor (continued). "Moreover, it is possible to suggest a role of the TRAF2-dependent TNFR2 signaling in the protection of MDSC from apoptosis and their accumulation during tumor growth." (PMID 40229245, 2025). "Further assessment demonstrated that the expression of necroptosis-related genes, including FADD, MLKL, TLR2, PGAM, HMGB1, CXCL 1, TRAF2, and EZH2, was elevated in tumor tissue, while FAS, RIPK1, RIPK3, TLR3, TNFRSF, ALDH2, and NDRG2 were upregulated in normal intestinal tissues." (PMID 40959081, 2025). "Moreover, single-cell profiling indicated that although the expression intensity of KHDC4 and TRAF2 in malignant cells was higher than in other clusters or cell types, the differences in the proportion of positive cells may be attributed to distinct tumor cell populations." (PMID 40560737, 2025). "Our analyses showed a significant correlation between TRAF2 expression and TMB and MSI status, suggesting a complex, interactive relationship between TRAF2 and tumor immune microenvironment, indicating that TRAF2 can regulate anti-tumor immune responses." (PMID 40144665, 2025). "An elevated TRAF2 protein levels were also confirmed by western blot and immunohistochemistry staining of HCC tissue microarray, consisting of 171 paired HCC samples and corresponding adjacent non-tumor tissues, based on the IHC staining intensity score." (PMID 37081115, 2023). "Although TRAF2 exhibits anti‐tumour activity via noncanonical NF‐κB, it has also been shown to elicit protooncogenic function by activating canonic NF‐κB signalling." (PMID 36881608, 2023). "Although current studies have primarily focused on improving anti-tumor responses through perturbations of TNF receptors (i.e., TNF receptor complex 1, TRAF2, and TRAIL receptors), future investigations should also explore the intracellular downstream signaling cascades." (PMID 37876793, 2023). "Based on a general description, how TRAF2 in concert with TRAF2-interacting proteins and other TRAF proteins act at the molecular level is discussed for its importance for tumor development and its potential usefulness as a therapeutic target in cancer therapy." (PMID 36011046, 2022). "Thus, as so often the activity of TRAF2 and TRAF3, here as tumor suppressors, require support by cIAP1 and cIAP2." (PMID 36011046, 2022). "Moreover, TRAF2 and the cIAPs have recently been identified as major targets facilitating CD8+ T-cell elimination of tumor cells in a TNF-dependent manner in vivo." (PMID 36339601, 2022). "Since we previously determined that both TRAF2 and STAT3 are suppressed by miR-671-5p to affect tumor migration, CSC ability and radioresistance in GBM, we attempted to identify the clinical connection between TRAF2 and STAT3 expression and disease progression." (PMID 35052701, 2021). "MSI1 may regulate GBM radioresistance, CSCs and tumor motility through miR-671-5p inhibition to increasing STAT3 and TRAF2 presentation." (PMID 35052701, 2021). "TRAF2 has been independently identified in recent functional work as the top hit in a genome-wide CRISPR screen for genes, that when knocked out, sensitize tumor cells to T cell-mediated elimination." (PMID 33508232, 2021). "Studies with IKKβ, TRAF2 and PERK knockout sub-lines of 786-O cells demonstrated that activation of both NF-κB and PERK was essential for sunitinib-induced production of IL-6 and IL-8 in tumor cells." (PMID 29515108, 2018). "We found that wogonoside could reduce the overexpression of TNF-α, TRAF2 and TRAF4 in later stage of tumor, and improved tumor microenvironment." (PMID 28774312, 2017). "These genes included tumor markers (MUC16), genes that control tumor migration (MYL9), metastasis (CEACAM6, VEGFC, CX3CL1, CST1, CCL5, S100A9, IGF1, NOTCH3), cell adhesion (FN1, CEACAM1), and inflammation (TRAF2, NF-κB2 and RelB)." (PMID 26090868, 2015).
tumor (continued). "DAB2IP has roles in both tumor initiation and metastasis, whereby DAB2IP controls primary tumor growth through activating Ras and drives metastasis through controlling NF-κB through regulation of TRAF2." (PMID 24912918, 2014). "In immortalized tumor cells, TWEAK activation of Fn14 recruits a TRAF2/cellular inhibitor of apoptosis 1 (cIAP1) complex that results in the lysosomal degradation of cIAP1-TRAF2 in a cIAP1-dependent manner." (PMID 24339827, 2013). "Interestingly, the absence of TRAF2 greatly enhances their sensitivity of tumor cells to immunotherapy." (PMID 40144665, 2025). "Here it is found that TRAF2 bound to the C‐terminal of CD47 cytoplasmic fragment and induced its ubiquitination, leading to inhibition of CD47 autophagic degradation by disrupting its binding to LC3, which in turn inhibited macrophage phagocytosis and promoted tumor immune escape." (PMID 39665172, 2025). "Additionally, CD27 upregulation in this subgroup coincides with that of TRAF2, the canonical adapter of CD27, which was identified as the top hit in a genome-wide CRISPR screen for genes that sensitize tumor cells to T-cell-mediated elimination when CD27 is knocked out58." (PMID 39300154, 2024). "In addition, miR-671-5p could attenuate tumor migration and cancer stem cell (CSC) characteristics by repressing the posttranscriptional activity of TRAF2." (PMID 35052701, 2021). "Immunohistochemistry staining demonstrated that in TRAF2-shRNA tumor tissue, the expression of Ki67, which is a well-known biomarker to predict cell proliferative potentials, significantly decreased, implying NPC cell proliferative capabilities were impaired after TRAF2 was silenced." (PMID 32566659, 2020). "For this gene in particular, we validated that different tumor cell lines may indeed not all be equally dependent on TRAF2 for their immune resistance, with some cell lines relying (more) on BIRC2, whereas others require inactivation of both genes in order to be sensitized to T cell challenge." (PMID 37398651, 2023). "Nevertheless, in the seven-gene model, the remaining four genes—PLK1, TRAF2, SLCO1B3, and ZEB2—though not consistently expressed in tumor epithelial cells, also exhibit either oncogenic or tumor-suppressive functions." (PMID 41187171, 2025). "Conversely, TRAF2, TRAF4, and TRAF7 displayed positive correlations with stromal, immune, and estimated scores, and negative correlations with tumor purity." (PMID 38825674, 2024).
cancer (113 papers, 2009 to 2026). A tumor composed of atypical neoplastic, often pleomorphic cells that invade other tissues. "Persistent NF-kB activation by TRAF2-dependent signaling pathways triggers the production of proinflammatory cytokines, which contribute to the survival and progression of cancer cells and are a hallmark of many inflammatory diseases." (PMID 40229245, 2025). "Mutations and aberrant DNA methylation are known to cause dysregulation of gene expression in cancer, and our findings are consistent with previous studies, indicating TRAF2 has a high rate of gene mutations." (PMID 40144665, 2025). "For this purpose, we analyzed the co-expression of genes associated with TRAF2 in the LinkedOmics database for 32 types of cancers and used heatmaps to display the top 50 genes that were positively or negatively correlated with TRAF2." (PMID 40144665, 2025). "We integrated genetics and histology for gene-disease network interaction analysis and demonstrated that TRAF2 is implicated in the progression of diseases in multiple domains, including cancer, hereditary diseases, aging, and neurodegenerative disorders." (PMID 40144665, 2025). "TRAF2 enhances proinflammatory signaling, positioning it as a key driver of cancer-associated inflammation." (PMID 40229245, 2025). "Tumor necrosis factor (TNF) receptor associated factor-2 (TRAF2) is an E3 ubiquitin ligase and scaffolding protein that contribute to the progression of various malignant tumors." (PMID 40144665, 2025). "In conclusion, TRAF2 is significantly overexpressed in 17 different cancer types and is strongly associated with poor prognosis." (PMID 40144665, 2025). "This study thoroughly analyzed the significant association between TRAF2 and the development of 33 different cancers." (PMID 40144665, 2025). "Our findings indicate that TRAF2 is frequently mutated and significantly overexpressed in various types of cancers, and this overexpression is linked to a poor prognosis." (PMID 40144665, 2025). "Intriguingly, the loss of TRAF2 sensitizes cancer cells to checkpoint inhibition, indicating that lowering the threshold for TNF cytotoxicity augments T-cell mediated killing." (PMID 38184997, 2024). "We previously reported that AWP1 binds to TNF receptor-associated factor 2 (TRAF2), which is involved in the NF-κB signaling pathway that plays a critical role in cancer cell migration." (PMID 33816268, 2021). "RACK1 or TRAF2 is an apoptotic molecule inactivated by SGs cause to impede cancer cell resistance to bortezomib." (PMID 35004322, 2021). "The mutation in CFLAR and TRAF2 destructthe apoptotic process and the cell follows the proliferation step and resulted to numerous numbers of cancer cells in the body." (PMID 34602774, 2021). "There are 237 different mutations of TRAF2 detected in human cancers, comprising 86% (205/237) mutations that change the protein sequence of TRAF2 and 14% (32/237) coding silent mutations." (PMID 30294322, 2018). "S1P also interacts with several intracellular targets that may play significant roles in cancer, including TNF receptor-associated factor 2 (TRAF2), HDAC, and human telomerase reverse transcriptase (hTERT)." (PMID 40002245, 2025). "TRAF2 has been identified as an oncogene frequently mutated in cancer." (PMID 40229245, 2025). "This could suggest that suppression of IKK1/α could possibly halt other pathways due to its wide array of interaction with other proteins, such as IKK2/β, AKT1, MAP4K4, and TRAF2, that are possibly implicated with other cancer pathways." (PMID 39062574, 2024). "Notably, TRAF2 levels decreased in pre-diagnostic plasma, whereas they increased at diagnosis, indicating varying levels during cancer development." (PMID 34888239, 2021).
cancer (continued). "Notably, 45% (92/205) of the coding-altering mutations of TRAF2 are recurrently detected in at least two cancer patients." (PMID 30294322, 2018). "As discussed for TRAF2, this phenomenon may be related to the mutational profile and malignant stage of the cancer cells as well as the nature of the environmental cue or treatment regimen." (PMID 30294322, 2018). "Interestingly, four mutation hotspots of TRAF2 are detected in more than 5 cancer patients, specifically P9, G10, R372, and Q457." (PMID 30294322, 2018). "Overall, TRAF2 was shown to positively correlate with the expression of genes associated with immune checkpoints in most cancer types, which supports the hypothesis that TRAF2 may be effective in cancer immunotherapy." (PMID 40144665, 2025). "Indeed, TRAF2 and TRAF2-associated proteins have been implicated in several ways in the crosstalk between autophagy, ER stress, cell death and inflammation, particularly in context of cancer development and cancer treatment." (PMID 36011046, 2022). "Moreover, the SphK1/SphK2 product, S1P was shown to target histone deacetylases (HDAC1/2), tumor necrosis factor receptor associated factor 2 (TRAF2), human telomerase reverse transcriptase (hTERT), and NF-κB nuclear activities linked to cancer initiation and progression." (PMID 33919234, 2021). "By linking the receptors to their downstream effectors, TRAF2 tightly regulates signaling pathways implied in many physiological and pathological processes, from inflammation to cancer." (PMID 40229245, 2025). "A growing body of research has significantly demonstrated that TRAF2 plays a prominent role as an oncogene in cancer." (PMID 40144665, 2025). "Currently, the molecular mechanisms of TRAF2 are mainly being investigated in specific cancer types, and its role in pan-cancer is unclear." (PMID 40144665, 2025). "The three cancer types with the highest correlation between TRAF2 and ESTIMATEScore were PAAD, LAML, and BLCA." (PMID 40144665, 2025). "Our study underscores the prognostic importance of TRAF2 in pan-cancer and its potential as a cancer immunotherapy target." (PMID 40144665, 2025). "It has been shown that TRAF2-dependent inhibition of apoptosis downstream of TNFRs is exploited by several cancers to escape from the T-cell killing." (PMID 40229245, 2025). "Antagonists of cIAPs, which also inhibit TRAF2, are being evaluated as anti-cancer agents in clinical trials but have shown limited efficacy." (PMID 40229245, 2025). "The interaction of TRAF2 with different protein partners has been identified to participate in the development of various cancer cells." (PMID 40560737, 2025). "Researchers are investigating natural and synthetic molecules that directly target TRAF2 or its interacting partners as potential anti-cancer strategies." (PMID 40229245, 2025). "The three cancer types with the strongest correlation between TRAF2 and StromalScore were PAAD, LAML, and LUAD." (PMID 40144665, 2025). "By analyzing the promoter methylation status of TRAF2 in cancers, it was observed that the methylation level decreased in 9 cancers and increased in 1 cancer." (PMID 40144665, 2025). "Although this study systematically reveals the role of TRAF2 in various cancers, limitations remain." (PMID 40144665, 2025). "TRAF2 is widely distributed in most cancer tissues, and its expression level is much higher than that in normal tissues." (PMID 40144665, 2025). "Since persistent stress conditions typically characterize the TME, the TRAF2-sustained ER stress response aids cancer cells and other TME components adapt to ER stress induced by chemotherapeutic agents, thus avoiding apoptosis and promoting chemoresistance." (PMID 40229245, 2025). "The widespread upregulation of TRAF2 suggests its potential significance in a wide range of cancer types, and through precise analysis of clinical prognostic data, we found that TRAF2 is a factor for poor prognosis in a wide range of cancers." (PMID 40144665, 2025).
cancer (continued). "The analysis of 33 cancer types revealed that TRAF2, TRAF3, TRAF4, and TRAF7 are predominantly overexpressed, whereas TRAF1, TRAF5, and TRAF6 exhibit lower expression levels." (PMID 38825674, 2024). "Increased expression of STRN was found in different cancers, which induced cell cycle progression and invasiveness by activating downstream transcription factors, including misshapen-like kinase 1, RhoA, TRAF2, NCK-interacting protein kinase and PDGFRA." (PMID 38215077, 2024). "As a mediator of TNF-α signaling, TRAF2 has been considered as a potential therapeutic target in cancers." (PMID 38698424, 2024). "Gene expression differential analysis of 539 ccRCC samples and 72 adjacent non-cancer samples revealed that TRAF2 was aberrantly elevated in ccRCC tissues compared with normal tissues (p < 0.0001)." (PMID 37415241, 2023). "TRAF2 is an important adaptor protein involved in several signal pathways, especially the NF-κB pathway, and is closely related to cancer development." (PMID 37081115, 2023). "In previous research, TRAF2 and TRAF3 are also the degradation factor of NIK protein and these proteins are frequently deleted and inactive mutated in several cancer types." (PMID 37005661, 2023). "With cancer development being a highly complex process and TRAF2 having varying roles under different cellular states, it is interesting to see the variation of TRAF2 levels in the plasma samples studied here." (PMID 34888239, 2021). "Collectively, we concluded that GPx1 functions as the master regulator of the ASK1-JNK-cFLIP-caspase-8 axis in apoptosis pathways via stimulation-dependent interaction with TRAF2 in cancer cells." (PMID 34158609, 2021). "USP1 function as an oncogene by interacting with DNA repair signal through PCNA and FANCD2, USP4 promote cancer progression by deubiquitinating TRAF2 and TRAF6 and thereby regulating the TGFβ signaling pathway." (PMID 34545063, 2021). "It has been reported that USP4 can deubiquitinate and stabilize TRAF2/TRAF6 to inhibit TNFα-induced cancer cell migration." (PMID 32549341, 2020). "The exact role of TRAF2 in a specific cancer type is likely dependent on the genetic alteration context, malignant stage of cancer, the nature of the environmental cue, and treatment regimen." (PMID 31130821, 2019). "A variety of TRAF2-dependent oncogenic pathways have been reported based on studies of patient samples, cultured human cancer cells or xenograft models." (PMID 30294322, 2018). "Gain-of-function alterations (gene amplification and overexpression) are common for TRAF1, TRAF4, TRAF5, and TRAF6 in human cancers, and are also identified for TRAF2 in epithelial cancers." (PMID 30294322, 2018). "Our recent work demonstrates that DR5 suppression promotes cancer cell invasion and metastasis through caspase-8/TRAF2-mediated activation of ERK and JNK signaling and MMP1 elevation." (PMID 28482915, 2017). "Involvement of TRAF2 in the positive regulation of cancer cell invasion has been suggested in some previous studies." (PMID 28482915, 2017). "Taken together, these data suggest that TRAF2 polyubiquitination plays an important role in mediating DR5-dependent modulation of cancer cell invasion." (PMID 28482915, 2017). "Suppression of TRAF2 inhibits the proliferation of several cancer cells, and the oncogene in epithelial cancers, TRAF2, contributing to the dysregulated NF-κB signaling pathway has been also identified." (PMID 26897165, 2016). "Agonistic antibodies to 4-1BB, OX40 and CD27 that are immune-stimulatory are being tested as potential immunotherapies for cancer patients and the efficacy of anti-4-1BB pre-clinically has been shown to depend on TRAF2-mediated NF-κB activation." (PMID 25648675, 2015). "Through genetic manipulation of DR5 expression in human cancer cells, we have shown that DR5 does indeed function as a suppressor of cancer invasion and metastasis, primarily via modulating caspase-8/TRAF2-mediated signaling." (PMID 26510914, 2015).